RBP4 (retinol binding protein 4)
Diseases named in the same sentence as RBP4 in open-access papers (continued):
Sharing a sentence is not in itself a finding about the gene and the disease.
Obesity (continued). "We then evaluated the circulating and GCF levels of RBP4 through ELISA analysis, and found an obesity-induced and/or periodontitis-induced elevated circulating level, with the maximum circulating RBP4 level in the OP group." (PMID 38069063, 2023). "A study analyzed RBP-4 in patients with obesity after weight reduction followed by an improvement in obesity-related medical problems and found that the systemic concentration of RBP4 was lower than that reported in some studies." (PMID 36462120, 2023). "Multiple regression analysis showed that VLDL subfraction is an independent predictor of RBP4 demonstrating the potential involvement of RBP4 in the lipid metabolism in obesity." (PMID 36837889, 2023). "RBP4 is a retinol transport protein in blood, expressed in the liver and adipose tissue and closely correlated with obesity and MetS." (PMID 36983885, 2023). "Several studies document that the RBP4 level was elevated in type 2 diabetes mellitus, obesity, and other diseases that are resistant to insulin." (PMID 36686076, 2022). "A previous study has shown that RBP4 levels are closely related to liver and kidney function in children with obesity." (PMID 35264110, 2022). "RBP4 levels are also correlated with obesity, hepatic steatosis, triglyceride levels and VLDL-cholesterol levels." (PMID 35496824, 2022). "Serum RBP4 levels are also found to be elevated in insulin-resistant mice and humans with obesity and diabetes." (PMID 35369314, 2022). "This suggests that a modest increase in circulating RBP4 secreted by the liver dose not impair glucose homeostasis and adipocytes are greater contributors to higher circulating levels of RBP4 in obesity." (PMID 35909571, 2022). "Obesity markers (leptin, neutrophil gelatinase-associated lipocalin (NGAL), retinol-binding protein 4 (RBP4), soluble intercellular adhesion molecule-1 (sICAM-1), and zinc alpha 2-glycoprotein (ZAG))." (PMID 35276788, 2022). "RBP4 is a useful biomarker for diagnosing obesity and the prognosis of related diseases, while IDH2 affects brown adipose tissue thermogenesis." (PMID 36467654, 2022). "Previous studies have reported that RBP4 is upregulated in insulin-resistant mice and is upregulated in the serum of patients with obesity or type 2 diabetes, thus affecting insulin signaling." (PMID 33461622, 2021). "Increasingly, elevated circulating RBP4 in both obesity and diabetes is generally believed to have double effects." (PMID 34373742, 2021). "Since our experiment was performed on Zucker rats with obesity induced by a mutation in the leptin receptor, we suggest that the body mass reduction obtained by IT procedure was substantial enough to lower RBP4 levels in animals with endogenous obesity." (PMID 33833309, 2021). "Elevated adipose tissue RBP4 expression has been demonstrated to contribute to IR in type 2 diabetes mellitus and obesity." (PMID 34177800, 2021). "Most adipokines, including leptin, tumor necrosis factor-alpha (TNF-α), interleukin 6 (IL-6), resistin, or retinol-binding protein 4 (RBP4), are augmented in the obese state and promote inflammatory reactions, leading to obesity-associated comorbidities." (PMID 34948320, 2021). "Recently, a growing body of evidence has indicated that RBP4 induces IR and is closely related to type 2 diabetes mellitus, obesity, metabolic syndrome, and cardiovascular disease." (PMID 34177800, 2021). "Recently, RBP4 has been reported to act as a bridge between obesity and cancer cell metabolism, and serum RBP4 levels in patients with HPA breast cancer have been reported to be significantly higher than those in control patients." (PMID 33834191, 2021). "Higher serum RBP4 levels were involved in obesity, type 2 diabetes, and in patients with cardiovascular disease." (PMID 34575030, 2021). "Numerous studies indicated a pathological level of RBP4 in obesity and diabetes; however, the results are partially contradictory." (PMID 34575030, 2021).
Obesity (continued). "RBP4 levels decreased by 16.7% and 19.6% in all obesity, 34.1% and 30.8% in males, 9.2% and 18.9% in females at 3 and 6 months after surgery respectively." (PMID 31956345, 2020). "RBP4 levels were only significantly and positively associated with HOMA-IR, SOD and negatively with the Matsuda index in males with obesity (all P < 0.05)." (PMID 31956345, 2020). "A study on 1033 Chinese subjects with various degrees of obesity has shown that Serum RBP4 levels were positively correlated with visceral adipose tissue (P < 0.001)." (PMID 31956345, 2020). "RBP4 has been recognized as an adipokine and as one of the oxidative stress markers involved in the pathogenesis of obesity-related metabolic diseases." (PMID 33198782, 2020). "Several studies reported an increased concentration of RBP4 in obesity and in conditions related to obesity complications, including metabolic syndrome, diabetes and cardiovascular diseases." (PMID 32095874, 2020). "As obesity, MetS and some adipokines contribute to the pathogenesis of osteoarthritis (OA), we investigated RBP4 in patients with OA." (PMID 32095874, 2020). "In this study, RBP4 levels were significantly and positively associated with TSH in obesity and the change in serum RBP4 levels were associated with change in TSH in 3rd month after LSG in males." (PMID 31956345, 2020). "An observational trial confirmed that people with obesity have higher levels of leptin, adipsin, retinol binding protein-4 (RBP-4), IL-6, high sensitivity-C reactive protein (Hs-CRP) and lower levels of adiponectin and visfatin as compared to lean people." (PMID 33511131, 2020). "Under lean conditions, adipocytes express about one-fifth as much RBP4 mRNA as a hepatocyte, while this expression increases substantially in obesity." (PMID 33135589, 2020). "There exists a positive association of RBP4 levels with oxidative stress markers such as SOD in males and females with obesity in this study." (PMID 31956345, 2020). "Some studies have reported the correlation between RBP4 and obesity as well as nonalcoholic fatty liver disease." (PMID 33082885, 2020). "RBP4 expression increases during obesity, and a previous study suggested that the development of obesity leads to the increased expression of RBP4 by adipocytes." (PMID 32156052, 2020). "We also measured the levels of DKK1 and RBP4, as metabolism-related humoral factors; the levels of both these components are reported to be increased in obesity." (PMID 33120884, 2020). "Obesity and accumulative fat storage increase secretion of RBP4 from adipose tissues and plasma concentration." (PMID 31953481, 2020). "It need be mentioned that RBP4 levels were slightly decreased from 3 months to 6 months after surgery without statistic difference in females, males and all subjects with obesity (all P > 0.05)." (PMID 31956345, 2020). "They demonstrated that serum RBP4 level was higher in humans with obesity and type 2 diabetes as well as in insulin-resistant mice." (PMID 31690939, 2020). "It is indicated that RBP4 concentrations are elevated in insulin-resistant mice and humans with obesity and diabetes and can be normalized by insulin-sensitizing drugs." (PMID 31956345, 2020). "Especially, RBP4 is produced by the visceral adipocytes under the status of obesity and insulin resistance." (PMID 31521168, 2019). "By contrast, the serum levels of RBP4 are shown to inversely associate with plasma HDL-C levels, pointing out that RBP4 has an essential role in promoting the pathological process of obesity." (PMID 31521168, 2019). "Vaspin belongs to family of newly discovered adipokines besides others such as retinol-binding protein 4 (RBP4), dipeptidyl peptidase 4 (DPP-4), bone morphogenetic protein (BMP)-4, BMP-7, and progranulin, recently implicated in various aspects of obesity." (PMID 31779136, 2019). "The RBP4/retinol ratio has therefore been advocated to better reflect alterations in obesity and T2DM." (PMID 31717719, 2019).
Obesity (continued). "The results in humans and rodent models established links between RBP4 expression and obesity, diabetes and other metabolic diseases." (PMID 31147589, 2019). "Initial studies documented that RBP4 levels were elevated in patients with obesity, impaired glucose tolerance and T2DM, and were correlated with HbA1c, fasting glucose and insulin." (PMID 31717719, 2019). "Whereas, the plasma concentration of RBP4 of individuals with obesity was markedly elevated (+43%, P = 0.04) in comparison with the lean subjects." (PMID 29335416, 2018). "We thus proposed that high level of RBP4, either from adipose tissues or cancer tissues, can promote cancer metastasis and obesity signaling, vice versa." (PMID 29642915, 2018). "Undoubtedly, the role of FABP4, sCD36, and RBP4 as the potential biomarkers of obesity, metabolic syndrome, and cardiovascular diseases was also confirmed in our studies." (PMID 29335416, 2018). "Several studies have reported elevated plasma RBP4 in T2DM subjects with obesity, impaired glucose tolerance, and T2DM with nephropathy." (PMID 29747616, 2018). "Susceptibility to diet-induced obesity and glucose intolerance in the APP (SWE)/PSEN1 (A246E) mouse model of Alzheimer's disease is associated with increased RBP4." (PMID 29479521, 2018). "Our data not only established RBP4 as a direct linkage between obesity and ovarian cancer, but also suggested RBP4 was a possible target for cancer treatment, especially in those associated with obesities." (PMID 29642915, 2018). "Several studies observed that RBP4 increased in obesity and its complications including T2DM, metabolic syndrome, and cardiovascular diseases as a chronic inflammatory state." (PMID 30186876, 2018). "In conclusion, we demonstrate that weight loss‐induced increases in RBP4 and decreases in FFA concentrations predict unfavorable long‐term weight changes in people with overweight and obesity." (PMID 29122953, 2017). "RBP-4 seems to be a cardiometabolic marker in chronic inflammatory diseases including obesity, type 2 diabetes, MetS and CVD." (PMID 28977161, 2017). "Here, we show for the first time that dietary weight loss‐induced changes in RBP4 and FFA concentrations independently predict weight regain over a 9‐month follow‐up period in people with overweight and obesity." (PMID 29122953, 2017). "Adipocyte-specific overexpression of (human) RBP4 aggravated diet-induced obesity, glucose intolerance, and hepatic TG levels." (PMID 29286303, 2017). "The level of RBP4 in the blood and adipose tissue appears to be increased in obesity and/or diabetes." (PMID 29023424, 2017). "We found an association of PTX-3 with risk factors such as obesity, uric acid, LDL-C, hsCRP, RBP-4 and adiponectin." (PMID 28977161, 2017). "The few studies that quantified both retinol and RBP4 in serum indeed confirm that a low retinol-to-RBP4 ratio is a better predictor for obesity, T2D, and other components of metabolic syndrome in children and adults then RBP4 alone." (PMID 29286303, 2017). "Results from the previous study also suggested that RBP4 levels had an important effect on obesity indices, as measured by BMI, WC, waist-to-hip ratio, and even body fat percentage." (PMID 26960804, 2016). "Retinol binding protein 4 (RBP4) is a recently identified adipokine that is elevated in patients with obesity or type 2 diabetes." (PMID 28002423, 2016). "Similar to prior studies in adults, we found that the RBP4 levels were positively correlated with most of the obesity indices in Chinese women, including BMI, waist circumference, and WHR in the whole subjects." (PMID 26960804, 2016). "Obesity have been closely related to occurrence and development of breast cancer, while elevated RBP4 levels were directly correlated with obesity." (PMID 28002423, 2016). "Previous studies revealed a correlation between serum RBP4 levels and obesity, dyslipidemia and FPG." (PMID 28002423, 2016).
Obesity (continued). "Increased serum RBP4 levels have been reported in subjects with obesity, IR, and T2DM and in other insulin-resistant states, such as metabolic syndrome and vascular complications of DM." (PMID 25922846, 2015). "RBP4 is an adipokine, secreted by adipocytes, that contributes to IR and obesity although there is some conflict between human and animal studies." (PMID 25830378, 2015). "In this context, we previously identified adiponectin, progranulin, chemerin, Fetuin-A and RBP4 serum concentrations as significant predictors of insulin sensitive or metabolically healthy obesity." (PMID 24968098, 2014). "In a study on RBP-4 in human obesity, it was shown that circulating RBP-4 levels were similar in normal weight, over-weight, and obese women, while in adipose tissue, it was positively correlate with GLUT 4 expression." (PMID 23573087, 2013). "According to some evidences, there are possible mechanisms that influencing diseases related to obesity and therapeutic opportunities for them through PPARγ and several adipokines such as vaspin and RBP4." (PMID 24330836, 2013). "In humans, circulating RBP4 levels were found to be highly negatively correlated with levels of insulin sensitivity, and to be increased with obesity and in those with type 2 diabetes." (PMID 22587616, 2012). "Serum RBP4 levels are elevated in insulin-resistant mice and humans with obesity and type 2 diabetes, and are normalized by rosiglitazone, a PPARγ agonist." (PMID 23145084, 2012). "The findings indicate that targeting RBP4 in brown fat might be a potential strategy for treating obesity." (PMID 40025173, 2025). "Thus, we selected IL-6 as the factor connecting inflammation to the growth of colorectal cancer and RBP4 as the link between obesity and tumorigenesis." (PMID 41007818, 2025). "Consequently, renal function is considered a major determinant of circulating RBP4 concentrations, which tend to accumulate in the context of metabolic disorders such as diabetes and obesity." (PMID 41303567, 2025). "Furthermore, the correlation between RBP4 levels and BMI, as well as the waist-to-hip ratio, is more pronounced in individuals with obesity." (PMID 40951890, 2025). "It is plausible that elevated RBP4 levels in obesity may promote cholesterol uptake, disrupt lipid homeostasis, and thereby facilitate influenza virus infection, potentially leading to disease progression." (PMID 41144502, 2025). "Furthermore, the significant correlation between RBP4 expression and obesity-related measures in our study supports the well-established role of RBP4 as an adipokine reflecting adipose tissue mass and visceral fat distribution." (PMID 41007818, 2025). "Taken together, our findings suggest that IL-6 and RBP4 may function as biomarkers of poor prognosis and may represent potential therapeutic targets, particularly in CRC cases linked to inflammation and obesity." (PMID 41007818, 2025). "This suggests that RBP4 plays a role in activating brown fat and could help in managing obesity and related metabolic disorders." (PMID 40025173, 2025). "Adipocytes produce RBP4, and its levels typically increase with obesity, which leads to the hypothesis that adipose tissue and hepatic-derived RBP4 could play different roles in cardiometabolic diseases." (PMID 39624361, 2024). "Furthermore, obesity and its consequences can lead to an imbalanced adipokine profile, increasing levels of proinflammatory adipokines and cytokines including retinol-binding protein 4, lipocalin 2, Leptin, and chemerin." (PMID 38898498, 2024). "Similarly, AdEVs-proteins (RBP4, perilipin-A, FABP, mimecan, TGFBI) and AdEVs-lipids (sphingolipids) have been linked to the obesity pathophysiology." (PMID 38988671, 2024). "Other studies have found similar results and suggest that RBP4 could be considered as a biomarker for obesity, metabolic syndrome, and type 2 diabetes." (PMID 37996653, 2024).
Obesity (continued). "However, in renal disease conditions such as diabetic nephropathy, obesity, or cancer, PTHrP increases markedly, as does RBP4." (PMID 39795999, 2024). "In leptin-deficient ob/ob mice, a genetic model of obesity, plasma levels of retinol-binding protein 4 were higher but bisretinoids in retina were not elevated." (PMID 37146972, 2023). "Additionally, RBP-4 is involved in numerous diseases, including cardiovascular disease, type 2 diabetes, metabolic dysfunctions, and obesity." (PMID 37711744, 2023). "Here, the circulating RBP4 level was not independently related to the comorbidity of periodontitis and obesity, while serum visfatin was significantly associated with periodontitis and obesity." (PMID 38132460, 2023). "Irisin and adiponectin levels decreased and RBP-4 levels increased in patients with obesity and DM." (PMID 37892122, 2023). "Thus, our results confirmed the previous data and showed novel findings of a correlation between serum adiponectin, irisin, and RBP-4 in OSAS patients with obesity and type 2 DM." (PMID 37892122, 2023). "This study investigated whether plasma irisin, RBP-4, and adiponectin levels are associated with the severity of OSAS in patients with obesity and type 2 diabetes mellitus (type 2 DM)." (PMID 37892122, 2023). "After we confirmed the normality by checking all variables using the Shapiro–Wilk normality test, we then assessed the correlations of RBP4/asprosin mRNA expression in the gingiva with other clinical and biomarker variables of obesity and periodontitis using Spearman correlation." (PMID 38069063, 2023). "Moreover, BPN-14136 administration to mice that overexpressed human RBP4 specifically in adipocytes partially prevented diet-induced obesity and hepatic steatosis, most likely via lowering circulating RBP4 levels." (PMID 35334893, 2022). "RBP4 is derived from adipose tissue, transports retinol (vitamin A) into the serum, and may act as a mediator between obesity and IR." (PMID 36293317, 2022). "Nevertheless, STRA6 expression is reduced in perigonadal AT and in the stromovascular fraction of the subcutaneous and perigonadal AT in mice models of diet-induced and genetically induced obesity, which possibly limits the anti-adipogenic potential of the RBP4/STRA6 axis." (PMID 35406450, 2022). "In addition, obesity can cause the body’s resistance to insulin, mediated in part by free fatty acids (FFA) and adipokines such as retinol binding protein-4 (RBP4) and resistin, which can reduce insulin sensitivity." (PMID 35216172, 2022). "Moreover, data are lacking about the relationship between impaired circulating fetuin-A and RBP4 production and the markers of obesity-related dyslipidemia (i.e., small HDL, mean LDL size etc.)in a special morbidly obese but non-diabetic population." (PMID 34575030, 2021). "RBP4 is produced by visceral adipose tissue in states of obesity and IR." (PMID 33671547, 2021). "Animal models give further insight into the role of RBP4 in obesity and diabetes." (PMID 34638803, 2021). "Changes in the production of adipokines such as leptin, resistin, lipocalin 2, tumor necrosis factor-α, chemerin, retinol binding protein 4, and interleukin-6 have been reported in obese individuals, and this can lead to the development of obesity-related metabolic diseases." (PMID 33498329, 2021). "Apart from markers of obesity and IR, RBP4 is also correlated with inflammatory factors." (PMID 33671547, 2021). "Our results may indicate a potential role of fetuin-A and RBP4 in impaired lipoprotein metabolism in obesity." (PMID 34575030, 2021). "RBP4 levels are elevated in insulin-resistant mice and humans with obesity and type 2 DM." (PMID 33671547, 2021). "In patients with obesity, RBP4 could play a pivotal role in atherosclerotic process; however, the link between RBP4 and lipid profile needs further extensive research." (PMID 33192583, 2020).